INS (insulin)
Diseases named in the same sentence as INS in open-access papers (continued):
Sharing a sentence is not in itself a finding about the gene and the disease.
type 2 diabetes (continued). "Impaired insulin signals contribute to an increase in oxidative stress, inflammatory cytokines, and abnormal lipid metabolism that will subsequently result in weight gain, metabolic syndrome, and type II diabetes mellitus if left untreated." (PMID 41141001, 2025). "We propose that the insulin-resistant and hyperinsulinemic environment observed in pregnancies affected by type 2 diabetes (T2D) may have contributed to increased secretion of AMH by the placenta." (PMID 40791992, 2025). "It is well established that exercise training effectively improves insulin sensitivity in healthy lean individuals, as well as in individuals with obesity and individuals with type 2 diabetes, and that insulin plays a key role in regulating protein synthesis, particularly in skeletal muscle." (PMID 40404819, 2025). "When comparing the diabetic groups, it was possible to observe that from the moment the tea was administered (day 28), the fasting blood glucose levels of these animals began to decrease until euthanasia, showing that the herbal medicine improves insulin sensitivity in type 2 diabetic rats." (PMID 41304970, 2025). "Here, we examined whether the ability of insulin to clear plasma BCAAs and any influence of acute exercise or exercise training on this response are intact in obesity and type 2 diabetes." (PMID 40404819, 2025). "Artificial intelligence (AI)–driven closed-loop insulin delivery systems are being explored in type 1 and type 2 diabetes, and their adaptation to pregnancy could provide more precise glycemic control." (PMID 40943638, 2025). "The study found no significant improvement in fasting blood glucose levels or overall glycemic control from the use of bedtime insulin supplementation in patients with type 2 diabetes, challenging current guidelines recommending routine bedtime supplementation for hyperglycemia correction." (PMID 39939862, 2025). "In type 2 diabetes, islets exhibited an increased alpha:beta cell ratio, altered spatial organisation with fewer beta-beta and more alpha-alpha interactions, and a significantly higher proportion of bi-hormonal cells co-expressing insulin and glucagon." (PMID 41059747, 2025). "For instance, the sons of mothers with type 2 diabetes had lower insulin concentrations compared with the sons of fathers with the same condition, while the daughters of mothers with type 2 diabetes had lower HDL-cholesterol levels compared with the daughters of fathers with type 2 diabetes." (PMID 40175764, 2025). "Moreover, for a study among insulin-treated type 2 diabetes patients, the 12-week and 3-day per week 4:3 diet achieved sustained weight reduction over a two-year follow-up and demonstrated excellent safety." (PMID 41536827, 2025). "The inclusion of individuals with both prediabetes and type 2 diabetes may introduce heterogeneity in insulin sensitivity and secretion patterns, reflecting different stages of disease progression." (PMID 40573137, 2025). "CGM is increasingly covered by payers for patients with type 2 diabetes on insulin." (PMID 40057678, 2025). "Insulin secretion and resistance are key pathophysiological factors in type 2 diabetes." (PMID 40296149, 2025). "Against this backdrop, we hypothesized that a potential explanation for elevated fasting insulin concentrations with impaired β‐cell function in youth with type 2 diabetes could be decreased metabolic clearance rate of insulin (MCRI)." (PMID 40470991, 2025). "Finally, intranasal insulin has emerged as a promising therapeutic approach for cognitive improvement, particularly in individuals with obesity or type 2 diabetes mellitus, offering potential benefits for addressing neurocognitive decline and improving memory." (PMID 40362522, 2025).
type 2 diabetes (continued). "Increasing the number of insulin-producing beta cells represents a promising therapeutic strategy that would improve the clinical outcome in both type 1 and type 2 diabetes patients by enhancing insulin secretion, improving glucose homeostasis and reducing the risk of secondary complications." (PMID 39774736, 2025). "A reduction in insulin demand has also been observed, indicating that IF may be an effective and safe adjunct treatment of type 2 diabetes, even in people on insulin therapy." (PMID 41458802, 2025). "In type 2 diabetes (T2D), insulin-resistant cells like adipocytes and myocytes release EVs containing abnormally expressed miRNAs, which in turn may disrupt insulin signaling mechanisms in recipient cells." (PMID 41446634, 2025). "Keywords used were icodec, insulin, type 1 diabetes, and type 2 diabetes." (PMID 40156735, 2025). "Additionally, the impact of probiotics on type 2 diabetes has been reported, contributing to better glycemic control and insulin sensitivity." (PMID 40725859, 2025). "Correlations between adiposity markers and insulin sensitivity also differed by ethnicity, suggesting that the pathways leading to type 2 diabetes may vary across populations." (PMID 40987939, 2025). "Furthermore, a large multicenter cross-sectional survey in China focusing on insulin injection techniques demonstrated that 97.81% of insulin-treated patients had type 2 diabetes, whereas only 2.19% had type 1 diabetes." (PMID 40900896, 2025). "Fasting glucose and/or insulin concentrations have been reported to be lowered following 8–10 passive heat exposure sessions in overweight individuals and patients with type II diabetes mellitus." (PMID 39373667, 2025). "A significant proportion of patients with type 2 diabetes will ultimately require insulin therapy." (PMID 40747308, 2025). "Finally, the COMBINE 3 trial (NCT05013229) compared once-weekly IcoSema with conventional basal-bolus therapy (glargine + insulin aspart) in 679 patients with type 2 diabetes insufficiently controlled on basal insulin." (PMID 40937414, 2025). "At the 18-year follow-up, mothers with GDM maintained higher FPG levels, HbA1c levels and fasting insulin levels and had a fivefold higher risk of type 2 diabetes than mothers without GDM (OR 5.17 [95% CI 2.10, 12.32])." (PMID 40603555, 2025). "Consequently, approximately 50% of individuals with type 2 diabetes require insulin therapy within 6–10 years of diagnosis." (PMID 41155203, 2025). "In addition, rising fasting plasma insulin levels are predictive of type 2 diabetes, a condition referred to as hyperinsulinemia." (PMID 40563879, 2025). "Since GPR40’s effects on insulin are glucose-dependent, it suggests that it could be a target for treating type 2 diabetes." (PMID 40671915, 2025). "Certain medications, particularly metformin and insulin, which are widely used in the treatment of type 2 diabetes, have anti‐inflammatory properties and may influence markers related to inflammation and oxidative stress." (PMID 40309648, 2025). "Type 2 diabetes (T2D) is characterized by insulin resistance or insufficient production of insulin." (PMID 39983050, 2025). "Thus, type 2 diabetes is characterized by insulin resistance in muscle and liver, coupled with a progressive loss of pancreatic insulin production." (PMID 41155203, 2025). "Moreover, for isCGM users with suboptimal glycaemic management and baseline HbA1c ≥58.5 mmol/mol (≥7.5%), reductions in HbA1c were higher than for the overall population of isCGM users with type 2 diabetes on basal insulin or multiple daily injections." (PMID 39460755, 2025). "Ileal interposition anticipates contact of food with the terminal ileum, promoting early release of incretin hormones such as GLP-1 and PYY, which reduce glucagon secretion and increase insulin sensitivity, being especially useful in patients with type 2 diabetes and preserved pancreatic reserve." (PMID 41446325, 2025).
type 2 diabetes (continued). "As type 2 diabetes progresses and beta cells lose their function, changes in the dopaminergic pathway may serve a different role than increasing insulin secretion." (PMID 40099262, 2025). "Additionally, the COMBINE 4 trial (NCT06269107) will compare icosema with glargine in insulin-naïve individuals with type 2 diabetes." (PMID 40937414, 2025). "We determined whether patients with type 2 diabetes (T2DM) adhered to PNE based on glycemic index (GI), glycemic load (GL), and food insulin index (FII) principles and whether adherence was associated with improved BGC." (PMID 40566351, 2025). "This disparity likely reflects the greater physiological complexity and variability inherent in Type 1 diabetes management, where autoimmune pancreatic destruction creates more unpredictable glucose-insulin dynamics compared to the metabolic dysfunction characteristic of Type 2 diabetes." (PMID 41295206, 2025). "Furthermore, some dedifferentiated β-cells co-express insulin and glucagon or glucagon alone both in rodents and in humans with type 2 diabetes, suggesting the transdifferentiation of β-cells into α-cells." (PMID 39860066, 2025). "In summary, these findings suggest that once-weekly insulin icodec may be a viable and safe treatment option for patients with type 2 diabetes." (PMID 38172995, 2024). "Additionally, one study showed that UCP2 variants (G174D and A268G) promoted insulin secretion, while another indicated that the UCP2 T/T variant increased the risk of type 2 diabetes." (PMID 39707176, 2024). "The link between EDCs, type II diabetes and MetS is attested by the adverse effects of EDCs on insulin secretion by the pancreatic β‐cells and by their peripheral actions, notably on muscle cells or adipocytes which are implicated in the development of insulin resistance." (PMID 39218795, 2024). "Many biology and health textbooks use the actions of insulin and glucagon to illustrate homeostasis and feedback mechanisms but stop short of examining important environmental and social factors that contribute to type 2 diabetes diagnoses." (PMID 38549950, 2024). "Assays of glucose uptake and glycogen synthesis were performed in additional myotubes from three donors with type 2 diabetes, where the glycogen synthesis response to insulin was robust (2.4-fold) in myotubes from one donor and blunted in two donors with type 2 diabetes." (PMID 38814443, 2024). "Type 2 diabetes, on the other hand, is related to age, weight, and lifestyle and is the most common type of diabetes among older people, mainly due to the body’s weakened response to insulin." (PMID 39650520, 2024). "Type II diabetes mellitus, mTOR (mechanistic target of rapamycin), insulin, cAMP (cyclicadenosine monophosphate) only upregulated at 78 vs. 58 in HN, glycerolipid metabolism, ErbB (erythroblastic oncogene B), arginine and proline metabolism only downregulated at 78 vs. 58 dpc in LW." (PMID 38441676, 2024). "The objective of this systematic review and meta-analysis was to examine the effects of plant-based diets on markers of insulin sensitivity in people with overweight/obesity, prediabetes, or type 2 diabetes compared with control diets (habitual or other diets)." (PMID 38999858, 2024). "A study showed that women with type 2 diabetes had significantly higher insulin levels in their breast milk compared to those with gestational diabetes and normal glucose tolerance, possibly due to insulin therapy and injections." (PMID 39021603, 2024). "Furthermore, no previous systematic review has assessed the effects of plant-based diets on markers of insulin sensitivity in people with prediabetes or type 2 diabetes." (PMID 38999858, 2024). "For instance, treating type 2 diabetes patients with thiazolidinediones could have the dual effects of improving insulin sensitivity and helping to alleviate the chronic inflammation associated with this patient population." (PMID 39763655, 2024).
type 2 diabetes (continued). "Mg supplementation may offer clinical benefits for individuals with type 2 diabetes by improving insulin sensitivity, enhancing glycemic control, and reducing complications." (PMID 39539878, 2024). "Insulin was administered to only 21% of refugees with poorly controlled type 2 diabetes." (PMID 39063405, 2024). "L. sylvestris has been shown to exert pharmacological properties such as antioxidant, alpha glucosidase inhibition and insulin secretagogue properties, thus making it a notable plant to be explored for its potential antidiabetic properties in models of type 2 diabetes." (PMID 39070783, 2024). "It is a well-recognised adverse event of treatment with insulin in patients with type 1 diabetes, but hypoglycaemia may receive less attention in patients with type 2 diabetes (T2D)." (PMID 39407915, 2024). "Type 2 diabetes is also a metabolic disorder, characterized by chronic hyperglycemia with disturbances of carbohydrate, fat and protein metabolism resulting from insufficient insulin secretion, insulin resistance or both." (PMID 38543143, 2024). "However, our findings are in line with the beta cell-specific Rfx6 knockout in adult mice and confirm the reported reduction of insulin secretion in islets from donors with type 2 diabetes as a result of reduced RFX6 levels." (PMID 38743124, 2024). "Compared with Lean-NGT, basal ISR was greater in the type 2 diabetes group (p<0.001), although fasting plasma insulin concentrations were similar, with the latter caused by the increase in fasting ICR in the type 2 diabetes group vs the Lean-NGT group (p=0.017)." (PMID 39138690, 2024). "Also, the reported symptom responses to hypoglycaemia were lower in people with type 1 diabetes than in people with long-standing insulin-treated type 2 diabetes, but remarkably well-preserved given the blunted counterregulatory hormone responses." (PMID 38376580, 2024). "The influence of type 2 diabetes, metformin, and insulin on COVID-19 was individually assessed." (PMID 39200096, 2024). "Furthermore, SCFAs have been found to improve insulin sensitivity, a key factor in managing blood glucose levels, particularly in individuals with Type II diabetes." (PMID 39734671, 2024). "Moreover, hepatic fat accumulation resulted in the decreased insulin activation of glycogen synthase and increased gluconeogenesis, similar to that found in people with impaired glucose tolerance/type 2 diabetes." (PMID 39769002, 2024). "DPP-4 inhibitors may be considered as the first-line treatment for individuals with type 2 diabetes when biguanides are difficult to use or when insulin secretion is impaired." (PMID 38256615, 2024). "Therefore, we analysed the glycogen synthesis data using only the more insulin-resistant myotubes, from five donors with type 2 diabetes." (PMID 38814443, 2024). "Within 10 months following the diagnosis of maturity onset diabetes of the young, she was successfully switched from multiple daily insulin injections to oral antidiabetic tablets (sulphonylurea) while maintaining stable glycemic control (HBA1c of 7.0%) and reducing hypoglycemia." (PMID 39420387, 2024). "Most patients with coronary artery disease and insulin use are type 2 diabetes." (PMID 39113013, 2024). "Known inhibitors of gluconeogenesis, metformin (a first-line treatment for type 2 diabetes), insulin, and AICAR (5-aminoimidazole-4-carboxamide riboside) as an AMPK activator inhibiting transcription of the gluconeogenesis genes, were used as the experimental control." (PMID 38399444, 2024). "The use of newer antidiabetic groups may delay the initiation of insulin therapy in type 2 diabetes, because the availability of these drug groups provides a wider choice for clinicians before considering insulin therapy." (PMID 38658983, 2024).
type 2 diabetes (continued). "Apart from the well-known calciotropic benefits of vitamin D, multiple clinical trials have demonstrated that supplementing with vitamin D in individuals with type 2 diabetes and metabolic syndrome improves insulin sensitivity, glycated hemoglobin (HbA1c), and lipid profiles." (PMID 39138505, 2024). "In conclusion, this comparative study showed modest attenuation of glucagon, adrenaline, and symptom responses to hypoglycaemia in people with type 1 diabetes and preserved responses in longstanding insulin-treated type 2 diabetes, possibly as a consequence of preserved beta cell function." (PMID 38376580, 2024). "For example, using a bioengineered skin microbe to help treat type 2 diabetes would require each bacterial cell to make between 0.03 and 300 molecules of insulin per second, presuming a bacterial density of 2 × 1013 to 2 × 109 bacteria per square centimeter of skin." (PMID 39104585, 2024). "Insulin resistance is a key feature of type 2 diabetes and several studies have documented the involvement of elevated ROS production in insulin resistant cells and tissues, which lead to disturbed signaling pathways that regulate the intracellular glycogen levels." (PMID 38397817, 2024). "However, the results strongly highlight lesser prescription of insulin therapy to patients with uncontrolled type 2 diabetes and with limited endogenous production of insulin in eastern India." (PMID 38654804, 2024). "Moreover, insulin secretion was found to be elevated before the development of hyperglycemia in a longitudinal study of Rhesus monkeys with a form of type 2 diabetes, which is similar to that found in humans." (PMID 39769002, 2024). "Secondly, among individuals with type 2 diabetes, carbohydrate-reduced or ketogenic diets (including the carnivore diet) could have further protective effects for bone mineralisation by improving insulin sensitivity." (PMID 39796574, 2024). "Impaired insulin sensitivity and an unfavourable inflammatory and adipokine profile have been demonstrated to be present years before the diagnosis of prediabetes or type 2 diabetes among South Asian individuals." (PMID 39097697, 2024). "Insulin is essential for treating type 1 diabetes and insulin-requiring type 2 diabetes." (PMID 39457586, 2024). "Additionally, previous studies have proven the effectiveness of HIFT in improving beta cell function as well as increasing insulin sensitivity in people with type 2 diabetes." (PMID 38691521, 2024). "Roxadustat treatment improved insulin action on glycogen synthesis in myotubes from donors with type 2 diabetes, suggesting that perturbations affecting the HIF pathway may be a novel way to improve metabolism in insulin-resistant individuals." (PMID 38814443, 2024). "Moreover, krill oil supplementation for 4 weeks improved endothelial dysfunction, high-density lipoprotein (HDL) profile and insulin sensitivity in subjects with type 2 diabetes." (PMID 39555189, 2024). "Aim of this study was to investigate in type 2 diabetes whether expression level of GALNT2, a positive modulator of insulin sensitivity, is associated with a metabolic signature." (PMID 38627282, 2024). "Lipotoxicity is particularly relevant in the context of insulin resistance, a condition where cells become less responsive to the effects of insulin, a hormone that regulates blood sugar, which is a common feature in obesity and type 2 diabetes." (PMID 38666853, 2024). "People with type 1 diabetes must be treated by insulin (through multiple daily injections or an insulin pump), whereas in type 2 diabetes, blood glucose levels are lowered, insulin sensitivity and insulin secretion is improved through oral medication, with metformin generally being the first choice." (PMID 39839113, 2024). "In summary, high-quality evidence demonstrates that both isCGM and rtCGM deliver glycaemic benefits for people with type 2 diabetes, whether treated with insulin or non-insulin therapy." (PMID 38951212, 2024).